GJA9 (gap junction protein alpha 9)
Description:
One gap junction consists of a cluster of closely packed pairs of transmembrane channels, the connexons, through which materials of low MW diffuse from one cell to a neighboring cell.
Synonyms: Cx58; Cx59; GJA10
Tractability: Antibody: UniProt places it where antibodies can reach, with medium confidence; UniProt predicts a signal peptide or a membrane-spanning region; its Gene Ontology location is reachable by antibodies, with medium confidence.
Gene: Protein-coding gene on chromosome 1 (38,874,069 to 38,881,587, reverse strand). Ensembl gene ENSG00000131233.
Subcellular location: Cell membrane; Cell junction, gap junction
Pathways (Reactome):
Vesicle-mediated transport: Gap junction assembly
Gene Ontology:
Molecular function: gap junction channel activity
Biological process: cell-cell signaling; cell communication; transmembrane transport
Cellular component: connexin complex; gap junction; plasma membrane
Genetic constraint (gnomAD): Loss-of-function variants: 1 observed, 1.31 expected, observed/expected ratio (o/e) 0.76, 90% interval 0.23 to 1.86. That is too few expected variants to judge how well the gene tolerates losing a copy. Missense variants: 538 observed, 620.58 expected, observed/expected ratio (o/e) 0.87, 90% interval 0.81 to 0.93. Synonymous variants: 186 observed, 227.62 expected, observed/expected ratio (o/e) 0.82, 90% interval 0.72 to 0.92.
Homologues: Orthologues: chimpanzee GJA9 (99% identical), pig GJA9 (80% identical), dog GJA9 (79% identical), rabbit GJA9 (69% identical), tropical clawed frog gja9 (49% identical), zebrafish gja9b (42% identical). Paralogues in human: GJA10 (39% identical), GJA8 (29% identical), GJA3 (27% identical), GJA5 (27% identical), GJA4 (26% identical), GJA1 (26% identical), GJC1 (24% identical), GJB1 (21% identical), GJB2 (20% identical), GJC2 (20% identical), GJB6 (20% identical), GJD2 (20% identical), and 8 more.
Diseases named in the same sentence as GJA9 in open-access papers:
GJA9 is named in the same sentence as 3 diseases in open-access papers, as found by Europe PMC text mining. Sharing a sentence is not in itself a finding about the gene and the disease. The quoted sentences say what the papers report.
cancer (1 paper, 2022). A tumor composed of atypical neoplastic, often pleomorphic cells that invade other tissues. "Gja9 belongs to the connexin family of proteins that constitute gap junctions, often compromised in cancers, including CRC." (PMID 35563010, 2022).
GJA9 also shares sentences with these, for which no sentence is quoted: laryngeal paralysis (1 paper); tumour (1).